CXCL10 (C-X-C motif chemokine ligand 10)
Diseases named in the same sentence as CXCL10 in open-access papers (continued):
Sharing a sentence is not in itself a finding about the gene and the disease.
Chagas disease (10 papers, 2012 to 2024). A parasitic infection caused by Trypanosoma cruzi. "Genotype and allele frequencies for the CXCL10 rs3921 polymorphism in patients with Chagas disease." (PMID 23150742, 2012). "Consistent with previous data, in addition to CXCL9, CXCL10 followed a similar trend, demonstrating higher levels in elderly patients with Chagas disease." (PMID 38139427, 2023). "Interestingly and in contrast with control individuals, levels of CXCL9 and CXCL10 continuously increased with age indicating that these two chemokines are strong markers of immunosenescence in the elderly with Chagas disease." (PMID 33262758, 2020). "Moreover, our data demonstrated that CXCL9 and CXCL10 increased in an age-dependent profile in Chagas disease patients." (PMID 32393333, 2020). "Regarding chemokines, CXCL10 and CCL5 were increased in IND and CCC patients compared to CTRL, while CCL2, CXCL9 and CXCL8 were reduced in both clinical forms of Chagas disease compared to CTRL." (PMID 38390336, 2024). "When compared to healthy controls, Chagas disease patients had higher circulating levels of IL-1-beta, CXCL9, and CXCL10 and lower levels of CCL5 than healthy subjects." (PMID 33262758, 2020). "Our results demonstrated that Chagas disease patients had higher serum levels of CXCL9, CXCL10 and IL-1β and lower serum levels of CCL5 than non-infected subjects." (PMID 32393333, 2020).
chronic obstructive pulmonary disease (10 papers, 2007 to 2025). A chronic and progressive lung disorder characterized by the loss of elasticity of the bronchial tree and the air sacs, destruction of the air sacs wall, thickening of the bronchial wall, and mucous accumulation in the bronchial tree. "Indeed, in the context of chronic obstructive pulmonary disease, the epigenetic reprogramming of p63 has been shown to be associated with a constitutive expression of transcripts such as CXCL10." (PMID 35066575, 2022). "In ASMC from people with chronic obstructive pulmonary disease (COPD), TNF-α induced CXCL10 via NF-κB activation, whereas IFNγ only induced a weak activation of NF-κB and activated STAT-1 as well, but not AP-1." (PMID 23034049, 2012). "Indeed, LXR activation by GW3965 has shown anti-inflammatory effects (reduction of CXCl10 and CCL5 levels) in lung macrophages from chronic obstructive pulmonary disease patients." (PMID 27149934, 2016). "Upregulation of CXCL10, the ligand of the chemokine receptor CXCR3 found on macrophages, has been observed in the bronchiolar epithelium of patients with Chronic Obstructive Pulmonary Disease (COPD) compared to non-smokers or smokers with normal lung function." (PMID 31681519, 2019).
colorectal tumors (10 papers, 2014 to 2025). "has shown that inhibition of TRIB3 signalling increases CD8+ T cell accumulation in colorectal tumours in a similar STAT3/STAT1/CXCL10 dependent mechanism." (PMID 39165364, 2024). "Since CCL5 and CXCL10 secretion is enhanced in colorectal tumors with strongtype-1 T-cell activity, the frequency of T-cells should correlate with secretionof both chemokines." (PMID 25671296, 2015). "In previous studies showed high expression level of CXCL9 and CXCL10 in colorectal tumors could promoted lymphocytes infiltrate into tumors, and suppressed tumor cells’ growth." (PMID 30973890, 2019). "In Visium spatial transcriptomics of human colorectal tumours, there were hotspots enriched in monocyte/macrophage genes (including CD14+CD68+), and expression of CXCL9 and CXCL10 were localised to these regions." (PMID 40523200, 2025). "Specifically, cytokines that were previously shown to correlate with the cytolytic index (C1QA, C1QB, C1QC, CXCL9, CXCL10, CXCL11 and CXCL13), were upregulated in CYT-high colorectal tumors." (PMID 31429779, 2019). "Also, induction of CXCL10 and CCL5 in colorectal tumors by hyperactivated NF-κB selectively promoted the accumulation of T effector lymphocytes but reduced the T regulatory lymphocytes." (PMID 24565056, 2014).
dermatomyositis (10 papers, 2014 to 2025). Dermatomyositis (DM) is a type of idiopathic inflammatory myopathy characterized by evocative skin lesions and symmetrical proximal muscle weakness. "Enriched genes including S100A12, MPO (myeloperoxidase), S100A8, CXCL10, S100A9, CD244, CD244,and TLR7 have been linked to dermatomyositis." (PMID 38137330, 2023). "CXCL10 expression on T cells in the perimysial infiltrates of dermatomyositis and CXCR3 expression on the majority of T cells in dermatomyositis were also reported." (PMID 24939012, 2014). "Juvenile-type dermatomyositis also showed high expression of CXCL10 in muscle tissue and the expression of CXCL10 and recruitment of CXCR3+ T cells were detected in the skin lesions of dermatomyositis." (PMID 24939012, 2014). "In support of this, interferon gamma and tumor necrosis factor alpha, which are increased in IIM, can induce secretion of the CXCR3 ligand CXCL10 by muscle fibers, and CXCR3+ T cells have been identified in the muscle biopsies of polymyositis, dermatomyositis, and inclusion body myositis patients." (PMID 35371068, 2022). "In addition to polymyositis, the CXCL10/CXCR3 axis was also reported to be involved in inclusion body myositis and dermatomyositis." (PMID 24939012, 2014). "In previous reports on IIMs, CXCL10 was abundantly expressed on macrophages and T cells in polymyositis, inclusion body myositis and dermatomyositis whereas CXCL9 and CXCL11 were not altered compared to the control." (PMID 24939012, 2014). "Similarly, the serum CXCL10 level is correlated with the Cutaneous Dermatomyositis Disease Area and Severity Index (CDASI) score in patients with DM." (PMID 40181992, 2025).
emphysema (10 papers, 2004 to 2024). "TNF-α, mainly produced by macrophages, can promote the expression of CXCL10, a potent chemoattractant recruiting neutrophils, monocytes, and T-helper type 1 cells, consequently, causing pulmonary emphysema." (PMID 35035511, 2022). "TNF-α and IFN-γ, which are predominantly produced by activated macrophages and lymphocytes, can trigger the release of CXCL10, a chemokine attracting monocytes, neutrophils, and T-cells, notably Th1 cells, thereby contributing to pulmonary emphysema." (PMID 38786103, 2024). "TNF-α, can induce the production of CXCL10, a potent chemoattractant for leukocytes such as monocytes, neutrophils and Th1 cells, and thus induces pulmonary emphysema." (PMID 34784929, 2021). "Importantly, CXCL10 was shown to control the secretion of elastolytic MMPs in lung tissue macrophages in former smokers with emphysema devoid of infection, suggesting autoinflammatory mechanisms in COPD35,46." (PMID 31619733, 2019). "A pulmonary airway model was designed, and morphological assessment of emphysema, IL-4, IFN-γ and CXCL10 concentration in bronchoalveolar lavage fluids, expression of CXCR3 and CXCL10 were detected." (PMID 31737787, 2019). "The degree of emphysema, concentration of IL-4, IFN-γ and CXCL10, and expression of CXCR3 and CXCL10 in mice administrated with low dose vitamin D3 were similar to the normally treated mice." (PMID 31737787, 2019). "Taken together, these data suggest that IL-17RA expression may be affecting two independent processes that are required for the development of emphysema, namely macrophage recruitment via CCL2 and induction of MMP12 by CXCL10." (PMID 21647421, 2011).
esophageal squamous cell carcinoma (10 papers, 2015 to 2025). Esophageal squamous cell carcinoma (ESCC) is a type of esophageal carcinoma (EC) that can affect any part of the esophagus, but is usually located in the upper or middle third. "A recent study showed that HDAC2 can bind to miR-503-5p and target CXCL10, thus promoting the progression of esophageal squamous cell carcinoma." (PMID 36189258, 2022). "In esophageal SCC, CXCL10 and CCL5 have been positively correlated with CD8 and Granzyme B at the mRNA level, and tissue expression of CCL5 was positively associated with post-surgical patient survival." (PMID 33925140, 2021). "We previously reported that high tumoral expression of Toll-like receptor 3 (TLR3) and CXCL10, a member of the CXC chemokine family, was an independent positive prognostic factor in patients with advanced thoracic esophageal squamous cell carcinoma (ESCC)." (PMID 40029556, 2025). "However, the expression of CCL5 and CXCL10 and its impact on the migration of CD8+ T lymphocytes remain unknown in patients with esophageal squamous cell carcinoma (ESCC)." (PMID 26317795, 2015). "Although esophageal squamous cell carcinoma (ESCC)-oriented mechanism has been widely explored, the integrated action of histone deacetylase 2 (HDAC2), microRNA (miR)-503-5p and C-X-C motif chemokine 10 (CXCL10) in ESCC has not been thoroughly explored." (PMID 33926524, 2021).
latent infection (10 papers, 2011 to 2025). "Here, we have shown that experimental latent infection of CD14+ monocytes, an established in vitro model system for latent infection in vivo, also results in changes to the cellular secretome causing upregulation of cIL-10, CCL8 and, in particular, CXCL10." (PMID 33912186, 2021). "In contrast to CD2 signaling, prestimulation of resting CD4 T cells with anti-CXCR4 antibody, with the chemokines CCL19/CCL21, or with IP-10 (CXCL10) has been shown to promote HIV-1 latent infection of resting CD4 T cells." (PMID 34765923, 2021). "We have analyzed the effect of HCMV latent infection on the secretome of CD14+ monocytes, identifying an upregulation of both CCL8 and CXCL10 chemokines in the CD14+ latency-associated secretome." (PMID 33912186, 2021).
Nephropathy (10 papers, 2016 to 2023). A nonspecific term referring to disease or damage of the kidneys. "Multiple reports have associated CXCL10 to nephropathy and suggested it as a marker for diagnosis and prognosis of the disease." (PMID 30620752, 2019). "CXCL10 is a molecule that suppresses angiogenesis and, hence, it may be concluded that the molecule might increase the nephropathy risk via either suppression of angiogenesis and tissue repair or elevation of inflammation." (PMID 34082771, 2021). "The gradual CXCL10 response we observed here, not only discloses that intrarenal BKPyV replication and CXCL10 secretion into urine and blood are functionally linked, but suggests its cumulative inflammatory effect on the occurrence of nephropathy." (PMID 31981424, 2020). "Moreover, of the chemokines that were upregulated during CKD, only CXCL10 was consistently elevated in cardiac tissue and plasma during folate induced nephropathy and after 5/6 nephrectomy." (PMID 35090403, 2022). "Therefore, it can be hypothesized that future investigations using specific antagonists for chemokines, for instance using antagonist for CXCL10 in nephropathy, can open an avenue to development of molecular therapy of polyomaviruses related disorders." (PMID 34082771, 2021). "Pro administration attenuated rI/R-induced kidney damage and renal TNF-α, IL-6, and CXCL-10 expression." (PMID 34111028, 2021). "Our previous investigations also proved the roles played by CXCL9, CXCL10 and CXCL11 in the induction of nephropathy in the BK virus infected patients who underwent kidney transplantation." (PMID 34082771, 2021).
neuroborreliosis (10 papers, 2013 to 2025). "CXCL10 has also been noted to be elevated in the cerebrospinal fluid of patients with neuroborreliosis." (PMID 39229265, 2024). "And human astrocytes and microvascular endothelial cells produce specific chemokines including CXCL10 to attract phagocytic cells and promote an inflammatory response in Borrelia burgdorferi infection." (PMID 36483597, 2022). "Previous work has shown elevated levels of CXCL9 and CXCL10 within the EM skin lesion and in the sera of patients with early acute Lyme disease, as well as in the synovial fluid and tissue of patients with Lyme arthritis." (PMID 24740099, 2014). "This is supported by the finding that chemokine (CXCL9 and CXCL10) and cytokine levels can vary in Lyme disease patients depending on the genotype of the infecting B. burgdorferi." (PMID 24740099, 2014). "When we compared the levels of serum CXCL9/CXCL10 among the acute Lyme patients with high liver enzyme levels, there was a significant association of high CXCL9/CXCL10 and CCL19 levels with elevated liver enzymes in the acute phase of Lyme disease." (PMID 24740099, 2014). "Similar to our observations, the levels of serum CXCL9 and CXCL10 can vary among acute Lyme disease patients and levels correlate with severity of disease." (PMID 24740099, 2014). "High levels of CXCL-10 are observed in the CNS of humans with neuroborreliosis." (PMID 23883071, 2013). "The levels of CXCL10 and CXCL8 in the CSF have previously been shown to be elevated both in patients with neuroborreliosis and with HIV‐negative neurosyphilis." (PMID 32419252, 2020). "CXCL9, CXCL10 and CCL19 are three prominent chemokines that were elevated in our cohort of acute Lyme disease patients." (PMID 24740099, 2014). "The coordinated elevation of CXCL9, CXCL10 and CCL19 in acute Lyme disease is consistent with an ongoing host immune response in the draining lymph nodes accompanied by the generation of Borrelia - reactive effector T cells and their migration into the site of infection." (PMID 24740099, 2014). "Indeed, it has been postulated that CXCL-10 creates a chemokine gradient between the CSF and serum and recruits CD4+ T-cells into the CSF of patients with neuroborreliosis." (PMID 23883071, 2013).
non-alcoholic steatohepatitis (10 papers, 2016 to 2025). "Our research group has previously demonstrated that DM509 treatment to non-alcoholic steatohepatitis mice decreased liver CXCR3, CXCL9, CXCL10, TNFα, IL-1β, and TGF-β expression." (PMID 38235144, 2023).
schizophrenia (10 papers, 2017 to 2025). A major psychotic disorder characterized by abnormalities in the perception or expression of reality. "Activation of TLR3 leading to an upregulation of IL-1β, CCL2, and CXCL10 are also seen in models of autism and schizophrenia associated with white matter abnormalities." (PMID 33558485, 2021). "Note that CXCL10 can also affect synaptic glutamate responses, so CXCL10 dysregulation may potentially exacerbate any latent dysfunction of glutamatergic transmission in subjects with genetic risk for schizophrenia." (PMID 30691477, 2019). "Since both elevated CXCL10 and supressed CXCL12 compromise developing GABAergic interneurons, the results support maternal immune challenge contributing to schizophrenia-associated neurodevelopmental abnormalities." (PMID 30691477, 2019). "Using five of these biomarkers (sTNF-R1 and sTNF-R2, CCL11, CXCL10, IL-4), the authors found a sensitivity of 70% and specificity of 89.4% for the diagnosis of schizophrenia." (PMID 28870209, 2017). "This study aimed to examine serum levels of Th17-related cytokines (IL-17, IL-21, IL-22, IL-23) and chemokines (CCL2, CCL5, CCL20, CXCL10, IL-8) in schizophrenia patients compared to healthy controls and to explore their associations with symptom severity and laboratory parameters." (PMID 41200225, 2025). "Furthermore, heightened neurotoxicity resulting from elevated concentrations of toxic cytokines (e.g., IL-1β, IL-6, IL-8, TNF-αand IFN-γ) and chemokines (e.g., CCL11, CCL2, CXCL8 and CXCL10) is markedly correlated with the schizophrenia phenome." (PMID 41200225, 2025). "Interestingly, CXCL10 levels have been different in different studies of schizophrenia." (PMID 41200225, 2025). "In addition, increased CXCL10 and decreased CXCL12 have been linked to impaired migration and function of cortical GABAergic interneurons and so may have particular relevance to schizophrenia risk." (PMID 30691477, 2019). "The present study compares the serum levels of selected cytokines and chemokines—IL-17, IL-22, IL-23, IL-8, IL-21, CCL20, CXCL10, CCL2and CCL5—in schizophrenia patients to healthy controls due to growing evidence linking immune-inflammatory and metabolic dysregulation to schizophrenia." (PMID 41200225, 2025). "In a study, the diagnosis of schizophrenia was accompanied by a specific cytokine-chemokine profile, i.e., increased levels of CCL11, CCL3, soluble TNF receptors 1 and 2 (sTNF-R1 and sTNF-R2), and decreased levels CXCL10 (also known as IFN-Υ-inducible protein 10 or IP-10), TNF-α, IL-2, and IL-4." (PMID 28870209, 2017).
squamous cell carcinoma (10 papers, 2012 to 2025). A carcinoma arising from squamous epithelial cells. "For instance, IL-1β is a marker of intraepithelial lesions in young women, and CXCL10 expression is a predictor of squamous cell carcinoma across all age groups." (PMID 38891028, 2024). "The depletion of CXCL10 in squamous cell carcinoma tumors by the use of neutralizing anti-CXCL10 antibodies resulted in a clear increase in their size." (PMID 24971349, 2014). "CXCL10 is a potential marker for response to radiotherapy and overall survival in patients with squamous cell carcinoma of the tongue." (PMID 24395654, 2014). "Additionally, nuclear localization of FAK increases certain cytokines like CCL5 and CXCL10 levels, suggesting a potential immune response and possible immunotherapeutic treatments in uveal melanoma patients as demonstrated in squamous cell carcinoma." (PMID 40000790, 2025). "Thus, in model systems of human NSCLC tumorigenesis in SCID mice inoculated with either adenocarcinoma or squamous cell carcinoma cell lines, the levels of CXCL10 were inversely correlated with tumor growth and resulted higher in squamous cell carcinoma compared with adenocarcinoma tumors." (PMID 24971349, 2014). "To investigate the anti-tumor effects of the IFN-inducible chemokines CXCL9, CXCL10, and CXCL11, we generated a cell line stably expressing these IFN-inducible chemokines using the mouse squamous cell carcinoma cell line SCCVII." (PMID 37218983, 2023).
viral hepatitis (10 papers, 2011 to 2025). An acute or chronic inflammation of the liver parenchyma caused by viruses. "The inflammatory hepatocytes secrete C-X-C motif chemokine 10 (CXCL10) which linked to the severity of liver damage involving viral hepatitis." (PMID 34676223, 2021). "CXCL10 is expressed by hepatocytes during chronic viral hepatitis, induced by LTβR activation via NF-κB and is considered as one of the main chemoattractants for tumour-infiltrating immune cells." (PMID 26206664, 2016). "Certain infections, including Helicobacter pylori and chronic viral hepatitis, elicit a significant propensity for the evolution of the thyroid nodules, possibly through the upregulation of specific mediators, including CXCL10 and tumor necrosis factor-α in the thyroid gland." (PMID 38068463, 2023). "Importantly, CXCL10 also has prognostic value in the treatment of viral hepatitis where CXCL10 levels follow disease recovery supporting our finding and proposes a prognostic role for CXCL10 in CHIKV." (PMID 21858242, 2011). "In the progression of chronic viral hepatitis, CCL5 and CXCL10 modulate the cytopathic and antiviral immune responses of natural killer cells and T lymphocytes." (PMID 40070835, 2025). "For each etiology-based subgroup (NAFLD, ALD, viral hepatitis, and “other”), CXCL5, CXCL9, and CXCL10 were significantly elevated in HCC patients and might be used as etiology-independent HCC-discriminant chemokine panel." (PMID 36982370, 2023).